CCT3 (chaperonin containing TCP1 subunit 3)
Diseases named in the same sentence as CCT3 in open-access papers (continued):
Sharing a sentence is not in itself a finding about the gene and the disease.
testicular cancer (1 paper, 2021). A primary or metastatic malignant neoplasm that affects the testis. "Moreover, downregulation of CCT3 has been reported in asthenozoospermic testicular cancer patients." (PMID 34697378, 2021).
tumor (41 papers, 2015 to 2025). "As a subunit of CCT, CCT3 is closely associated with the expression of tumor-related proteins, genes, and cell cycle regulatory proteins, such as cell cycle regulators and STAT3." (PMID 39928781, 2025). "CCT3 promotes tumor progression through multiple signaling pathways and is linked to immune cell infiltration and immune checkpoint expression in the tumor microenvironment, presenting a new potential target for overcoming drug resistance in various cancers." (PMID 39928781, 2025). "This study demonstrates that circRNA CCT3 is a diagnostic and prognostic biomarker in BCa patients and is a tumor promoter in BCa." (PMID 37833621, 2023). "Early studies reported the biological results of CCT3 deficiency in tumor cells were phenotypical, and affected growth, motility, cell cycle and apoptosis." (PMID 35409343, 2022). "Low levels of circ-CCT3 are strongly associated with higher survival and tumor metastasis in CRC patients." (PMID 36185198, 2022). "Collectively, CCT3 had the potential to be a diagnostic and prognostic biomarker for multiple tumor types." (PMID 36313331, 2022). "In clinical subgroup analysis, expression of CCT3 was associated with higher cancer stages and tumor grades." (PMID 34505628, 2021). "CCT3 shows promise as a diagnostic biomarker and may be a novel target for immunotherapy across multiple tumor types." (PMID 39928781, 2025). "It was discovered that circRNA CCT3 expression was elevated in BCa patients, suggesting that circRNA CCT3 is highly expressed in BCa and may be associated with tumor development." (PMID 37833621, 2023). "CCT3 had the potential to be a diagnostic and prognostic biomarker for multiple tumor types." (PMID 36313331, 2022). "Given its correlation with tumor stages and grades, CCT3 may act as a new diagnostic biomarker." (PMID 36313331, 2022). "In this review, we summarize the basic structure and function of chaperonin containing TCP-1 complex and CCT3, and discuss the role of CCT3 in tumor development." (PMID 39928781, 2025). "For example, in several gastrointestinal malignancies, circ-CCT3 promotes tumor growth by sponging tumor-suppressor miRNAs such as miR-1287-5p, miR-378a-3p and miR-613." (PMID 41153715, 2025). "In gastrointestinal malignancies, circ-CCT3 promotes tumor growth by sponging tumor-suppressor miRNAs." (PMID 41153715, 2025). "In nude mouse experiments, knocking down CCT3 suppressed tumor growth, significantly reducing tumor volume and weight." (PMID 39928781, 2025). "CCT3 promotes tumor proliferation, Sorafenib resistance, and ferroptosis sensitivity, while CCT6A regulates the G1‐to‐S phase transition, contributing to cell cycle dysregulation and tumor progression." (PMID 41312091, 2025). "circ-CCT3 functions as a competitive endogenous RNA (ceRNA), sponging tumor-suppressive miRNAs and subsequently modulating the expression of oncogenic transcripts." (PMID 41153715, 2025). "In CRC cell models, CCT3 depletion reduces cellular viability and impairs colony formation, hindering tumor growth." (PMID 41153715, 2025). "Based on these results, sorafenib had an enhanced ferroptosis-inducing and tumor suppressive effect when CCT3 was knocked down in vivo." (PMID 39210442, 2024). "In accordance with our in vitro findings, sustained depletion of CCT3 in conjunction with sorafenib led to a marked decrease in tumor volume and mass." (PMID 39210442, 2024). "CCT3 mRNA was found to be significantly upregulated in tumor tissues of 18 cancer species including LUAD." (PMID 36918801, 2023). "In this study, we provide further multi-scale dataset evidence that CCT3 mRNA is significantly upregulated in 18 cancer species while downregulated in tumor tissues of kidney chromophobe (KICH) and kidney renal clear cell carcinoma (KIRC)." (PMID 36918801, 2023).
tumor (continued). "On the other hand, scatter dot plot displaying RNA-seq expression levels from TCGA LUAD dataset also revealed that CCT3 mRNA expression was substantially higher in tumor than that in normal lung tissues (P = 2.287e-33, Normal = 59 and Tumor = 535)." (PMID 36918801, 2023). "Collectively, these findings suggest that CCT3 expression is closely related to tumor progression, sex and smoking status of LUAD patients." (PMID 36918801, 2023). "LUAD tumor tissues had significantly higher level of CCT3 protein expression than normal lung tissues (P = 2.464e-18, Normal = 111 and Primary tumor = 111)." (PMID 36918801, 2023). "Integrated analyzes identify CCT3 as a modulator to shape immunosuppressive tumor microenvironment in LUAD and therefore, a prognostic factor for LUAD." (PMID 36918801, 2023). "We found a strong H3K27ac signal in CCT3 promoter region by the WashU database in various tumor cells." (PMID 36313331, 2022). "In the tumor microenvironment, CCT3 expression was negatively relevant with immune cell infiltration and immune checkpoint genes expression." (PMID 36313331, 2022). "In our study, we also demonstrated that depletion of CCT3 significantly inhibits tumor growth and metastasis in vivo and in vitro." (PMID 35409343, 2022). "This suggested that knockdown of CCT3 not only inhibited tumor growth but also repressed the metastasis of LUAD." (PMID 35409343, 2022). "CCT3-KD and LINC00326-OE resulted in a significant suppression in tumour growth in comparison to the respective controls confirming that low CCT3 and high LINC00326 gene expression reduced tumour burden." (PMID 35022268, 2022). "By bioinformatic analysis, we found that the mRNA and protein levels of CCT3 were abnormally elevated in most tumor types and were correlated with poor prognosis." (PMID 36313331, 2022). "Next, we further verified CCT3’s function on tumor growth in an orthotopic model and found significant decreases in total lung weight and tumor area when CCT3 expression was ablated." (PMID 35409343, 2022). "The current findings suggest that CCT3 is a significant oncogene in PTC, and it was found that an increase in CCT3 expression was associated with the tumor area of PTC." (PMID 36185198, 2022). "Our study observed an abnormal increase of CCT3 expression in multiple immune cells of the tumor microenvironment based on single-cell sequencing data." (PMID 36313331, 2022). "And we observed a close link between CCT3 expression and tumor grades of multiple cancer types, including CESC, KIRC, LIHC, STAD and UCEC." (PMID 36313331, 2022). "We discovered that CCT3 expression was negatively relevant with immune cell infiltration in most of tumor types." (PMID 36313331, 2022). "Gene set enrichment analysis (GSEA)analysis indicated that high expression of CCT3 was closely correlated with tumor-related signaling pathway mTOR pathway (MTORC1/PI3K AKT mTOR) and HNSCC cell survival." (PMID 36185198, 2022). "CCT3 knockdown mice xenografts had a smaller tumor volume and less weight than the control group (P < 0.05)." (PMID 35399722, 2022). "Animal studies showed that silencing CCT3 dramatically inhibited tumor growth and metastasis of LUAD." (PMID 35409343, 2022). "Subsequently, The investigation of nude mouse xenograft models strongly supported that the knockdown of CCT3 significantly suppressed tumor growth." (PMID 35399722, 2022). "Animal studies show that silencing CCT3 significantly inhibits the tumor growth and metastasis of LUAD." (PMID 35409343, 2022). "Next, we calculated CCT3 expression levels in different tumor tissues by analyzing the CCLE datasets." (PMID 36313331, 2022). "QPCR assay validated that CCT3 mRNA levels in the colon normal cell line-FHC was lower than those in the COAD tumor cell lines." (PMID 36313331, 2022).
tumor (continued). "Then, the expression of CCT3 in tumor tissues was compared with which in normal samples by using ONCOMINE databases." (PMID 34505628, 2021). "The abnormal expression of CCT3 has been proved to influent the migration of tumor cells and the prognosis of cancer patients in previous researches." (PMID 34505628, 2021). "Regarding the tumor grade, significant up-regulation of CCT3 expression was found in grade 2 and grade 3 patients than in grade 1 patients." (PMID 34505628, 2021). "In kidney chromophobe (KICH), the expression of CCT3 was higher in normal tissues than in tumor tissues." (PMID 34505628, 2021). "Third, more molecular experiments should be performed to uncover how the expression of CCT3 regulates growth and invasion of tumor cells to affect the progress of HNSCC in vivo and in vitro." (PMID 34505628, 2021). "The results showed that up-regulated CCT3 was found in metastatic tumor tissues compared with primary tumor tissues." (PMID 34505628, 2021). "GSEA analysis indicated that CCT3 was closely correlated with tumor-related signaling pathways and HNSCC cell survival." (PMID 34505628, 2021). "Chaperonin containing TCP1 complex subunit 3 (CCT3) is a crucial subunit in the complexes and involved in tumor cell proliferation and the tumorigenesis." (PMID 32923383, 2020). "Knocking down CCT3 significantly suppressed cell proliferation, colony formation in soft agar, and tumour growth in mice models, while elevated caspase 3/7 activity." (PMID 31501420, 2019). "CCT3 expression levels were correlated with etiology, tumor size, and pathological stage." (PMID 39928781, 2025). "Silencing CCT3 inhibits tumor cell growth, proliferation, and promotes apoptosis." (PMID 39928781, 2025). "Consequently, it is imperative to conduct further research to investigate the impact of CCT3 on the tumor immune microenvironment." (PMID 39210442, 2024). "Furthermore, the intensity of 4-HNE in tumor specimens from the CCT3 knockdown cohort surpassed that of the control group post-sorafenib therapy, suggesting heightened oxidative stress within the tumor." (PMID 39210442, 2024). "In HCC, CCT3 accelerates tumour growth by regulating lipid metabolism." (PMID 38363102, 2024). "CCT3-mediated Th2 deviation in tumor microenvironment may link to a worse outcome for LUAD, since Th2 cytokines IL-4 IL-5, IL-9 and IL-13 trigger the differentiation of tumor-associated M2 macrophages." (PMID 36918801, 2023). "Furthermore, both CPTAC and HPA database analyses showed the overexpression of CCT3 protein in LUAD tumor tissues." (PMID 36918801, 2023). "Thus, dysregulation of CCT3 is characteristic of immune cell infiltration in tumor microenvironment and a better understanding of CCT-related immunosuppression will be conducive to immunotherapy for LUAD." (PMID 36918801, 2023). "Next, circRNA CCT3 in BCa tumor progression was further investigated in cells." (PMID 37833621, 2023). "The tumor growth was significantly suppressed upon CCT3 knockdown." (PMID 35409343, 2022). "CCT3 expression was higher in tumor tissues than that in adjacent counterparts (P < 0.05)." (PMID 35399722, 2022). "Considering that CCT3 showed higher expression levels in both cancer cells and tumor microenvironment in COAD and STAD than other tumors, we wondered whether targeting CCT3 was feasible in gastrointestinal tumor." (PMID 36313331, 2022). "Considering that CCT3 was relevant with an immunosuppressive tumor microenvironment, we assumed whether CCT3 overexpression lead to immune escape?" (PMID 36313331, 2022). "Particularly, the highest cancer type of CCT3 expression in the tumor microenvironment was COAD." (PMID 36313331, 2022). "In this work, we explored these processes in LUAD cells and observed consistent results, which implies that the role of CCT3 in tumor cells is conserved and could be a common target for cancer therapy." (PMID 35409343, 2022). "Previous studies elucidated that CCT3 promoted tumor cell proliferation by mediating YAP activity." (PMID 36313331, 2022).
tumor (continued). "Knockdown of CCT3 induces apoptosis and inhibits tumor proliferation." (PMID 35409343, 2022). "In conclusion, CCT3 expression was relevant with immunosuppressive tumor microenvironment." (PMID 36313331, 2022). "CCT3 expression was relevant with an immunosuppressive tumor microenvironment." (PMID 36313331, 2022). "Similarly, we affirmed that the tumor patients with high-expressed CCT3 showed poor prognosis, demonstrating its potential as a prognostic biomarker for multiple tumor types." (PMID 36313331, 2022). "Among them, CCT3 was identified as being critical for tumor growth and metastasis of LUAD." (PMID 35409343, 2022). "Additionally, we found that the CCT3 knockdown groups developed less local invasion of tumor cells in comparison with the control groups." (PMID 35409343, 2022). "Research: Tumor-repopulating cells (TRCs)Achievement: CCT3 inhibits TRCs-induced tumor formation." (PMID 36185198, 2022). "In vivo, tumor growth in the nude mice was significantly inhibited after CCT3 silencing." (PMID 35399722, 2022). "Interestingly, among the CCT3 high-expressed 8 tumors, other than in malignant cells, we also found an abnormal increase of CCT3 expression in multiple immune cells of the tumor microenvironment in CHOL, COAD, NSCLC and STAD." (PMID 36313331, 2022). "We also noticed that knockdown of CCT3 dramatically reduced the size and weight of the tumor." (PMID 35409343, 2022). "CCT3 expression was significantly increased in tumor tissues than in normal oral samples." (PMID 34505628, 2021). "CCT3 was overexpressed in tumor tissues of HNSCC than corresponding normal tissue." (PMID 34505628, 2021). "In addition, the protein expression level of CCT3 was closely related to HCC tumor size, TNM stage, and Child-Pugh classification." (PMID 34676169, 2021). "Since CCT3 was associated with the progress of HNSCC, we investigated the CERES dependence scores of HNSCC cell lines to determine the importance of CCT3 for survival of tumor cells." (PMID 34505628, 2021). "Notably, with Ttl, S100a4, Zfx, Cct3, Stat3, Stab1 and Bmx, 7/20 found candidate genes have been reported as proliferation-related in tumor cells too." (PMID 29228606, 2017). "The results showed suppressed in vivo tumor growth with CCT3 knockdown." (PMID 29340068, 2017). "Moreover, CCT3 knockdown enhanced the anti-tumor effects of Sorafenib in nude mice." (PMID 39210442, 2024). "Whether these two drugs play their roles of anti-tumor by targeting CCT3?" (PMID 36313331, 2022). "Furthermore, the DNA methylation levels of CCT3 were lower in tumor tissues than normal tissues." (PMID 36313331, 2022). "All the data suggest CCT3 might be a prognostic biomarker for a number of tumor types." (PMID 36313331, 2022). "In addition, the expression of CCT3 in metastatic lesions was higher than in primary tumor tissues." (PMID 34505628, 2021). "Moreover, we found that ASPM, NEK and CCT3 over-expression present significant association with overall survival of HCC patients based on TCGA validation, predicting enhanced invasive/metastatic potential of HCC and higher risk of early tumor recurrence." (PMID 28086821, 2017). "CCT3, as one of the subunits of the CCT, plays a key role in tumor cell growth, proliferation, cell cycle regulation, and survival." (PMID 39928781, 2025). "All six amplifications that led to a substantial increase in expression in tumor samples were also reported as up-regulated HSP when comparing normal and tumor tissues (CCT3, HSPA6, DNAJA3, TRAP1, DNAJC5, and DNAJC5B)." (PMID 38816397, 2024). "According to GSE32863 sequencing data, increased expression of CCT3, CCT4, CCT5, CCT6A, CCT7, and CCT8 was observed in LUAD tumor tissues compared with paired normal tissues." (PMID 39259093, 2024). "NAT10, CCT3, PLEK2, HOXB7, FOXD1, SEC61G, and so on have been identified as tumor markers in HNSCC by performing TCGA HNSCC database analysis." (PMID 37679666, 2023).
tumor (continued). "Collectively, these findings established interaction network for CCT3 and depicted LUAD-specific protein-protein and genetic interaction networks to gain insight into the tumor-promoting effects of CCT3 in LUAD." (PMID 36918801, 2023). "The oncogenic role of CCT3 was investigated by establishing CCT3-related genetic and PPI networks, enrichment of signaling pathways and infiltration of immune cells in the tumor microenvironment of LUAD." (PMID 36918801, 2023). "It has been widely reported that CCT3, a subunit of CCT/TRiC complex, has tumor-promoting effects in various malignancies including LUAD." (PMID 36918801, 2023). "In this work, we identified that CCT3 is up-regulated in LUAD and positively correlated with tumor malignancy." (PMID 35409343, 2022). "CCT3, a survival hazard gene identified in this study, was overexpressed in NSCLC tumor B cells and suppressive tumor Tregs of CD4-C9-CTLA cells vs. other tumor infiltrating Tregs of CD4-C8-FOXP3 cells." (PMID 35804895, 2022). "In particular, for AFP-negative and small HCC patients, the CCT3 protein level showed good correlation with HCC etiology, tumor size, TNM stage, and Child-Pugh classification." (PMID 36185198, 2022). "It has been demonstrated that CCT3 expression is up-regulated in HCC, which in turn affects tumor progression and prognosis." (PMID 36263426, 2022). "Of this group of genes, HSPD1, HSPE1, CCT3 and CCT5 were overexpressed in Basal, HER2 and Luminal B subtypes (more aggressive BRCA tumours)." (PMID 29954368, 2018). "In this work, we found that concentration of serum CCT3 and IQGAP3 in patients with HCC was correlated with etiology, tumor size, number of cancer nodules and child-pugh classification, indicating that they are novel predictors for HCC." (PMID 27390551, 2016). "CCT3 and IQGAP3 protein level correlated well with HCC etiology, tumor size, TNM stage, and child-pugh classification." (PMID 27390551, 2016). "Proteins important for tumor cell survival (SND1), proteins known to be expressed by MM cells (PPA1, CCT3, NME1, SPAG9), and a marker for bone resorption (DPYD) were detected at higher levels in the NBM coculture supernatants." (PMID 26545722, 2015). "While CCT3 exhibits moderate basal expression in gastrointestinal epithelium, it is markedly overexpressed in CRC, with both mRNA and protein levels found significantly elevated compared to adjacent non-tumor tissues." (PMID 41153715, 2025). "Thus, CCT3 mRNA and protein levels are both augmented in LUAD samples through comparative analyses across normal and tumor tissues." (PMID 36918801, 2023). "In summary, our results indicated that subunits of TRiC displayed varying degrees of abnormal expressions, and CCT2, CCT3, CCT5, CCT6A, CCT7, and CCT8 were significantly upregulated in BCa patients and their upregulation was positively correlated with BCa tumor stage." (PMID 33815471, 2021). "Therefore our study adds evidence to an important role of CCT3 and CCT5 in the more aggressive BRCA tumours: Basal, HER2 and Luminal B subtypes." (PMID 29954368, 2018). "Furthermore, based on TCGA or GEO datasets, we found a negative correlation between CCT3 high expression and the OS of multiple tumor types by Kaplan-Meier Plotter and GEPIA2 databases." (PMID 36313331, 2022). "That means that the tumor patients with high CCT3 expression may not be suitable for immune checkpoint inhibitors, contributing to selecting the exact patients." (PMID 36313331, 2022). "In addition, unlike adjacent non-tumour specimens, tumour specimens with higher CCT3 often had higher YAP/TFCP2, and vice versa." (PMID 31501420, 2019).